SLC7A5 (solute carrier family 7 member 5)
Diseases named in the same sentence as SLC7A5 in open-access papers (continued):
Sharing a sentence is not in itself a finding about the gene and the disease.
breast cancer (continued). "In support of this finding, we have previously along with others reported that SLC7A5 high expression correlates with poor clinical outcome and poor response to endocrine therapy in patients with luminal breast cancer." (PMID 32545448, 2020). "Specifically, patients with SLC7A5+SLC3A2+ tumours were significantly associated with disease recurrence, distant metastasis and a high risk of death from breast cancer (p < 0.05) compared with the other subgroups, which showed better clinical outcome." (PMID 32093034, 2020). "In patients treated with endocrine therapy, high SLC7A5/SLC3A2 co-expression was associated with poor patient outcome, and depletion of SLC7A5/SLC3A2 using siRNA increased the sensitivity of breast cancer cells to tamoxifen." (PMID 32093034, 2020). "In this study, we aim to evaluate the predictive value of the co-expression of the SLC7A5/SLC3A2 complex as a clinical marker of benefit from endocrine therapy in early ER+ breast cancer." (PMID 32093034, 2020). "Previous genomic and TMA studies of large breast cancer cohorts have shown that LAT1 (SLC7A5) is a prognostic indicator of poor patient outcome in luminal B subtype only." (PMID 32458655, 2020). "In this study, we showed the clinicopathological significance and prognostic utility of the SLC7A5/SLC3A2 complex in predicting the benefit of endocrine treatment in patients with ER+ breast cancer." (PMID 32093034, 2020). "The predictive value of SLC7A5/SLC3A2 co-expression regarding the benefit from endocrine therapy will require further investigation in clinical trials of primary breast cancer treatment." (PMID 32093034, 2020). "This study aims to assess the effects and roles of SLC7A5/SLC3A2 co-expression in predicting responses to endocrine therapy in patients with ER+ breast cancer." (PMID 32093034, 2020). "The biological and clinical impact of SLC7A5/SLC3A2 co-expression was assessed in large annotated cohorts of ER+/HER2− breast cancer with long-term follow-up at the mRNA and protein levels." (PMID 32093034, 2020). "SLC7A5 is highly expressed in the breast cancer cell lines MCF-7 and MDA-MB-231, with higher upregulation in MCF-7 cells than in MDA-MB-231 cells." (PMID 29562706, 2018). "One meta-analysis investigating gene expression-based biomarkers in breast cancer revealed that SLC7A5 is a prognostic factor for breast cancer." (PMID 29562706, 2018). "Association between SLC7A5 mRNA and PAM50 subtypes was confirmed using the Breast Cancer Gene-Expression Miner v4.0." (PMID 29566741, 2018). "An in vivo study showed that paclitaxel-loaded SLC7A5-targeting poly(lactic-co-glycolic acid) nanoparticles exhibited cytotoxicity, cellular uptake, and in vivo antitumor effects in breast cancer." (PMID 29562706, 2018). "In locally advanced breast cancer, SLC7A5 and carcinoembryonic antigen-related adhesion molecules (CEACAM5 and CEACAM6) predict poor response of neoadjuvant chemotherapy." (PMID 29562706, 2018). "Overall, considering the expression of SLC7A5/SLC3A2 in breast cancer patients could predict failure in endocrine therapy and guide the choice of other alternative therapies." (PMID 38705513, 2024). "SLC7A5 expression is observed in all molecular biological subtypes of breast cancer." (PMID 39852119, 2024). "Importantly, a study revealed the relation between SLC7A5 overexpression and tamoxifen resistance in breast cancer cells, and silencing SLC7A5 expression was sufficient to increase the sensitivity of cancer cells to tamoxifen." (PMID 38705513, 2024). "Apparently, this is why SLC7A5 is expressed in all subtypes of breast cancer." (PMID 39852119, 2024). "Additionally, SLC7A5 serves as a pivotal regulatory factor in the treatment of various cancers, including multiple myeloma, breast cancer, and gastric cancer, and represents a potential therapeutic target for overcoming patient resistance." (PMID 39234254, 2024).
breast cancer (continued). "Among the cationic amino acid transporter/glycoprotein-associated family, SLC7A5, SLC7A7, and SLC7A8 are highly expressed in luminal subtypes of breast cancer, as well as SLC7A9 and SLC7A10, the activity of which is observed exclusively in the case of positive HER2 expression." (PMID 39852119, 2024). "Studying the biological role of SLC7A5 in breast cancer may lead to its identification as a novel tumor biomarker and target in corresponding therapeutics." (PMID 37731509, 2023). "SLC7A5 upregulation may serve as an adaptation to hypoxia, which has previously been suggested in clinical breast cancer samples." (PMID 38082346, 2023). "A previous study also showed that SLC7A5 regulated AKT/mTOR activation in breast cancer." (PMID 35986300, 2022). "This study aimed to assess the effects of LLGL2/SLC7A5 co-expression in predicting prognosis and response to tamoxifen therapy in ERα-positive breast cancer patients according to LLGL2/SLC7A5 mRNA and protein expression in long-term follow-up invasive breast cancer tissues." (PMID 36192404, 2022). "We also evaluated the expression levels of SLC7A5 protein in breast cancer tissue samples." (PMID 36192404, 2022). "To further investigate whether SLC7A5/SLC3A2 co-expression affects the response of ER+ breast cancer cells to tamoxifen, we knocked down SLC7A5 and SLC3A2 in combinations in MCF7 and MDA-MB-175-VII cells using siRNAs." (PMID 32093034, 2020). "Here we showed that high co-expression of the SLC7A5/SLC3A2 complex could be used as a prognostic marker to predict a poor response to endocrine treatment in ER+ breast cancer." (PMID 32093034, 2020). "In addition, SLC7A5 expression is consistently induced in a panel of breast cancer cell lines subjected to hypoxia." (PMID 33321829, 2020). "On the basis of our findings, SLC7A5/SLC3A2 co-expression has the potential of identifying a subgroup of ER+/HER2− breast cancer patients who fail to benefit from endocrine therapy and could guide the choice of other alternative therapies." (PMID 32093034, 2020). "Despite our data demonstrating the prognostic and predictive utility of SLC7A5/SLC3A2 co-expression in ER+ breast cancer, the exact mechanism of how the heterodimeric complex of SLC7A5/SLC3A2 contributes to endocrine resistance is unclear and requires further mechanistic investigations." (PMID 32093034, 2020). "Recent studies showed that high expression of different AA transporters, such as SLC3A2 or SLC7A5, is related to poor outcomes in the luminal B ER+ breast cancer subtype, suggesting that this subtype might be particularly vulnerable to glutamine depletion." (PMID 31152137, 2019). "Over expression of SLC7A5 appears to play a role in the proliferation and progression of the aggressive ER+ subtype of breast cancer, thus it could act as a potential therapeutic target." (PMID 29566741, 2018). "Six of the 11 non-mitosis related genes were previously associated with poor survival in breast cancer patients: KRT17, MMP12, SLC7A5, SQLE, GABRP and PA2G4, but the remaining 5 had not been previously associated with cancer risk: CCDC86, NUP107, NUTF2, WASF1 and ELOVL6." (PMID 23077491, 2012). "Thus, the co-expression of ASCT2, SLC7A5 and SLC3A2 may serve as potential biomarkers for identifying ER+ highly proliferative subclass and HER2+ subclass of breast cancer patients at higher risk of poor response to endocrine therapy." (PMID 41154605, 2025). "Also, overexpression of SLC7A5 in HER2-negative breast cancer types was shown in a study." (PMID 38705513, 2024).
breast cancer (continued). "Also, in estrogen-receptor (ER) positive breast cancer cells, it was revealed that co-expression of SLC7A5/SLC3A2 leads to increased proliferation in cancer cells and is associated with poor prognosis, while their knocking down using siRNA-sensitized breast cancer cells to tamoxifen." (PMID 38705513, 2024). "Therefore, we hypothesized that both LLGL2 and SLC7A5 are required for the efficacy of tamoxifen treatment in ERα-positive breast cancer patients." (PMID 36192404, 2022). "Furthermore, SLC7A5 protein expression was observed in 10% of breast cancer tissues." (PMID 36192404, 2022). "As such, SLC7A5 might play an important role in the pathogenesis of breast cancer." (PMID 35328298, 2022). "Knockdown of SLC7A5 and SLC3A2 resulted in reduced proliferation of ER+ breast cancer cells and enhanced the sensitivity of ER+ breast cancer cells to tamoxifen." (PMID 41154605, 2025). "Key transporters, such as SLC1A5 (also known as ASCT2) and SLC7A5 (LAT1), facilitate glutamine and essential amino acid uptake, respectively, and are upregulated in various breast cancer subtypes." (PMID 39973065, 2025). "It has been demonstrated that SLC1A5, SLC6A14, SLC7A11, SLC3A1, SLC7A5, SLC38A2, and SLC38A5 are significantly expressed in breast cancer cells." (PMID 39973065, 2025). "The increased expression of ATP13A4 (breast cancer), ATP13A3 (pancreatic and neuroblastoma cancers), and SLC3A2/SLC7A5 (LAT1) in various cancers suggest their potential as therapeutic targets through the inhibition of polyamine transport." (PMID 40724997, 2025). "Analysis of breast cancer data from the TCGA database revealed a strong positive correlation between IRF5 expression and that of SLC7A5 and IDO1." (PMID 41179282, 2025). "SLC7A5 (LAT1) is generally overexpressed in cancer cells, including breast cancer of luminal and TNBC types, in which LAT1/CD98 overexpression serves as a prognostic marker." (PMID 40221767, 2025). "Both SLC7A5 and IDO1 exhibited markedly elevated expression in breast cancer tissues, with the highest levels observed in triple-negative breast cancer subtypes." (PMID 41179282, 2025). "SLC7A5 is crucial in fulfilling cancer cells’ elevated amino acid demand, particularly in TNBC, HER2-positive, and luminal B breast carcinomas (the majority in our samples)." (PMID 38256136, 2024). "The two amino acid transporters SLC7A5 and SLC7A11 are considered essential for the growth of breast cancer cells in a cell-dependent manner." (PMID 37754258, 2023). "According to the type of breast cancer (i.e., HER2+ or ER+), several amino acid transporters, such as SLC1A5, SLC6A14 and SLC7A5, were shown to have different expressions in BC tissue compared to controls." (PMID 37628869, 2023). "This suggests a potential of CoCl2 to upregulate SLC7A5 and exploring LAT1-inhibiting drug impacts on breast cancer cells, offering valuable insights for future studies." (PMID 38082346, 2023). "Researchers have shown that SLC7A5 and SLC6A14 are upregulated in several cancers of epithelial origin, including breast cancer." (PMID 37238741, 2023). "3-[123I]-α-methyl-l-tyrosine (IMT) is an artificial amino acid that is transported through SLC7A5 and is also a suitable metabolic indicator for SPECT in extracranial tumors, including breast cancer." (PMID 37754258, 2023). "In summary, we showed that low LLGL2/SLC7A5 mRNA co-expression (LLGL2low/SLC7A5low) was an independent favorable prognostic factor in ERα-positive breast cancer patients, as well as low LLGL2 or low SLC7A5 mRNA expression." (PMID 36192404, 2022). "Unexpectedly, SCRIB and SLC3A2 form a quaternary complex with LLGL2-SLC7A5 to promote membrane assembly of the SLC7A5/SLC3A2 amino acid transporter complex, which is needed for leucine uptake and proliferation of ER+ breast cancer cells in culture and in vivo." (PMID 35501367, 2022).
breast cancer (continued). "Human breast cancer cells, including MCF-7, were shown to express LAT1 (SLC7A5) and LAT2 (SLC7A8); however, only SLC6A14 requires chloride ions for its activity." (PMID 34359969, 2021). "Despite several studies that have shown the prognostic role of SLC7A5 or SLC3A2 in cancers, the relation of their co-expression with endocrine therapy efficacy in ER+/HER2− breast cancer has yet to be reported." (PMID 32093034, 2020). "We found that proliferation-related genes are highly expressed in a subgroup of patients with high SLC7A5/SLC3A2, and knockdown of SLC7A5/SLC3A2 decreased proliferation of ER+ breast cancer cells." (PMID 32093034, 2020). "Our study further establishes the impact of SLC7A5/SLC3A2 co-expression on the clinical outcome and efficacy of adjuvant endocrine treatment in a large cohort of patients with ER+ breast cancer." (PMID 32093034, 2020). "3-[123I] Iodo-α-methyl-l-tyrosine (IMT) is an artificial amino acid that is transported via SLC7A5, as well as a suitable metabolic tracer for SPECT in extracranial tumors including breast cancer." (PMID 29562706, 2018). "Immunohistochemical analysis of human breast cancer tissues has shown that HER-2 and TNBC types show higher expression of SLC7A5 than luminal A and B types." (PMID 29562706, 2018). "Treatment of breast cancer cells with iodine/iodide results in upregulation of ACR1C1 and SLC7A5, the two genes that were upregulated by DIO1 overexpression in our study." (PMID 29272308, 2017). "MiR-126-3p was also reported to suppress breast cancer cell growth by targeting insulin receptor substrate-1 (IRS-1), and inhibit proliferation of small cell lung cancer cells by targeting SLC7A5." (PMID 26244545, 2015). "We were able to show that FXYD3 and PTX3 expression is associated with poor overall patient survival in SCC patients and LAD1, SLC7A5, SLPI, NID2, SPOCK1 and SULF1 correlated significantly with impaired pCR in breast cancer patients." (PMID 23251436, 2012). "In addition, LLGL2 regulates SLC7A5 by forming a trimeric complex with SLC7A5 and YKT6, enhancing leucine import, and thereby controlling ER+ breast cancer cell proliferation." (PMID 38705513, 2024). "SLC1A5, SLC3A2, SLC7A5, and SLC6A14 may be promising biomarkers for BC [breast cancer] diagnosis and may represent potential therapeutic targets for these patients”." (PMID 37627015, 2023). "However, the protein levels of SLC7A11 in ER+ breast cancer cell lines are quite lower than in ER− breast cancer cells, suggesting that SCRIB-SLC3A2 complex mainly targets SLC7A5 in ER+ breast cancer cells." (PMID 35501367, 2022). "SLC7A5 (solute carrier family 7 member 5 or LAT1) is a transporter of large branched-chain and aromatic neutral amino acids and is highly expressed in breast cancer, non-Hodgkin's lymphoma and colorectal cancer and positively associated with poor prognoses." (PMID 35986300, 2022). "Despite the role of glutamine metabolism in promoting tumor progression being well documented, the potential roles of these transporters are less investigated particularly in terms of endocrine resistance in luminal breast cancer, apart from SLC38A2 and SLC7A5." (PMID 34282517, 2021). "This was consistent when analysing protein expression, where SLC7A5+SLC3A2+ co-expression was shown to predict a high risk of distant metastasis and death from breast cancer (p < 0.05), but not recurrence (p = 0.25)." (PMID 32093034, 2020). "In breast cancer, glutamine is a key nutrient for cancer cell proliferation and survival, and it is largely regulated by amino acid transporters, especially SLC1A5 and SLC7A5." (PMID 29562706, 2018). "Some amino acid transporters, including SLC1A5, SLC6A14, SLC7A5, and SLC7A11, may be promising targets for the treatment of breast cancer since they modulate tumor growth, metastasis, treatment response, and prognosis of breast cancer." (PMID 29562706, 2018).
breast cancer (continued). "The relationship between high SLC7A5 mRNA expression and poor patient outcome in ER+ disease, but not ER- disease, was confirmed using Breast Cancer Gene-Expression Miner." (PMID 29566741, 2018). "SLC7A5 protein expression was observed, predominantly in the membrane of invasive breast cancer cells, with expression levels varying from absent to high." (PMID 29566741, 2018). "From the downregulated genes of the EMT-core gene list, low FXYD3 expression showed a trend to poor overall survival of SCC patients (p = 0.17) and low expression of LAD1 (p = 0.00074), SLC7A5 (p = 0.0093) and SLPI (p = 0.043) significantly correlated with worse pCR of breast cancer patients." (PMID 23251436, 2012). "Using the JASPAR algorithm to predict transcription factor binding sites, we detected IRF5 binding motifs within the promoter regions of SLC7A5 and IDO1, suggesting that IRF5 may transcriptionally activate these genes, thereby enhancing tryptophan metabolism in breast cancer cells." (PMID 41179282, 2025). "To investigate the importance of SLC7A5 in TNBC tumor tissue, we performed single cell analysis based on scRNA-seq datasets of TNBC from public database (Combined Single-Cell and Spatial Transcriptomics Reveal the Metabolic Evolvement of Breast Cancer during Early Dissemination GSE176078)." (PMID 37731509, 2023). "Furthermore, SLC7A5 is a candidate molecular target for cancer therapeutics and inhibition of transport with JPH203 (Nanvuranlat) significantly suppressed the proliferation of estrogen deprivation-resistant (EDR) breast carcinoma cell lines." (PMID 35986300, 2022). "Positive SLC7A5 expression (>15 H-score) was observed in 191/1110 (17%) and 268/1554 (17%) of cases in the discovery and validation sets, respectively, while high SLC7A5 mRNA expression (log2 intensity >8) was observed in 1019/1923 (53%) of the METABRIC breast cancer cases." (PMID 29566741, 2018). "Thus, our study showed that the co-expression of LLGL2 and SLC7A5 mRNA is a promising candidate biomarker and suggested that the LLGL2–SLC7A5 axis might be a therapeutic target in early breast cancer patients, especially in those receiving adjuvant tamoxifen therapy." (PMID 36192404, 2022).